SIL1 (SIL1 nucleotide exchange factor)
Diseases named in the same sentence as SIL1 in open-access papers:
SIL1 is named in the same sentence as 43 diseases in open-access papers, as found by Europe PMC text mining. Sharing a sentence is not in itself a finding about the gene and the disease. The quoted sentences say what the papers report.
Marinesco-Sjögren syndrome (31 papers, 2010 to 2026). "Causative mutations in SIL1 are associated with the rare genetic disorder Marinesco-Sjögren syndrome (MSS)." (PMID 35698232, 2022). "Woozy mice carrying a Sil1 mutation recapitulating Marinesco-Sjögren syndrome (i.e., rare, early onset, autosomal recessive multisystem disorder with cerebellar ataxia, cataracts and myopathy)." (PMID 35615361, 2022). "Loss of SIL1′s function is the leading cause of Marinesco-Sjögren syndrome (MSS), an autosomal recessive, multisystem disorder." (PMID 33557244, 2021). "Biallelic mutations in the BiP co-chaperone SIL1 cause Marinesco–Sjögren syndrome (MSS) in humans, a condition characterized by cataracts, early-onset cerebellar ataxia, cognitive deficits, short stature, and progressive vacuolar myopathy." (PMID 34692675, 2021). "Sil1 was identified as the causal gene of Marinesco-Sjӧgren Syndrome by two independent research groups in 2005." (PMID 31531014, 2019). "Background and objective: Recessive mutations in the SIL1 gene cause Marinesco-Sjögren syndrome (MSS), a rare neuropediatric disorder." (PMID 31258504, 2019). "In 2005, two groups independently identified SIL1 (gene ID: 64374) as the causative gene of Marinesco-Sjӧgren Syndrome (MSS; OMIM 248800)." (PMID 31531014, 2019). "Mutations in SIL1, a cofactor for the endoplasmic reticulum (ER)-localized Hsp70 chaperone, BiP, cause Marinesco-Sjögren syndrome (MSS), an autosomal recessive disorder." (PMID 29666155, 2018). "It has been shown that recessive SIL1 mutations are found in ~60% of patients with the clinical Marinesco-Sjögren syndrome triad (myopathy, early-onset cataracts, and cerebellar ataxia)." (PMID 28052128, 2017). "Mutations in the SIL1 gene cause Marinesco-Sjögren syndrome (MSS), an autosomal recessive disease characterized by cerebellar ataxia, mental retardation, congenital cataracts, and myopathy." (PMID 27792754, 2016). "Mutations of SIL1 cause Marinesco-Sjögren syndrome (MSS), which is a neurodegenerative disorder." (PMID 36006904, 2022). "Marinesco–Sjögren syndrome is a multisystemic early onset disorder caused by mutations in the SIL1 (SIL1 Nucleotide Exchange Factor) gene, which encodes a nuclear exchange factor for the endoplasmic reticulum resident chaperone BiP (binding immunoglobulin protein)." (PMID 33917666, 2021). "Interestingly, the clinical phenotype of patients with congenital mutations in the SIL1 gene (Marinesco-Sjogren syndrome) overlaps with the phenotype of COG4-G516R patients (Saul-Wilson syndrome)." (PMID 34603392, 2021). "Sil1 is the causative gene of Marinesco-Sjӧgren Syndrome (MSS)." (PMID 31531014, 2019). "Interestingly, comparable phenotypes have been observed in the course of pathophysiological analyses of SIL1, a causative co-chaperone gene of Marinesco-Sjogren syndrome, in which ID is a major symptom." (PMID 24658322, 2014). "While unique functions for SIL1 in either BiP-mediated folding or degradation of endogenous clients have largely eluded identification, the discovery that mutations in SIL1 are the leading cause of Marinesco-Sjögren syndrome (MSS) indicates that there are SIL1-specific functions." (PMID 29666155, 2018). "There is no cure for Marinesco-Sjögren syndrome (MSS), a genetic multisystem disease linked to loss-of-function mutations in the SIL1 gene, encoding a BiP co-chaperone." (PMID 39804912, 2025). "Marinesco–Sjogren syndrome (MSS) is a rare multisystem pediatric disorder, caused by loss-of-function mutations in the gene encoding the endoplasmic reticulum cochaperone SIL1." (PMID 34830330, 2021). "We report in this study the first genetically confirmed case of Algerian patient with Marinesco-Sjögren syndrome (MSS) and the characterization of a new mutation in the SIL1 gene, c.1285 T > G; p.Tyr429Asp, at the homozygous state." (PMID 26068213, 2015). "In the cases of CMRD-MSS (Marinesco-Sjogren Syndrome), there is, in addition to a mutation in the SAR1B gene, a mutation in the SIL1 gene." (PMID 21235735, 2011).
Ataxia (14 papers, 2006 to 2025). Ataxia refers to impaired coordination of voluntary muscle movement. "SIL1-null woozy mutant mice exhibit progressive ataxia caused by loss of Purkinje cells via ER stress, together with myopathy." (PMID 27792754, 2016). "SIL1-deficient woozy mutant mice exhibit progressive ataxia caused by the loss of Purkinje cells via ER stress." (PMID 24755310, 2014). "MSS is an AR disorder, caused by mutations in SIL1, characterized by cerebellar atrophy with ataxia, early-onset cataracts, and it also may include mild to severe intellectual disability, hypogonadism and skeletal abnormalities." (PMID 38334933, 2024). "This hypothesis is supported by studies on the SIL1-KO (SIL1 gene knockout), which exhibits SIL1 loss-of-function, leading to an unfolded protein response, abnormal protein accumulation, and neurodegeneration in cerebellar Purkinje cells, culminating in ataxia." (PMID 41465794, 2025). "The first instance where SIL1-deficient mice provided mechanistic insights into MSS-related pathologies came from studies to understand the cerebral deterioration and severe ataxia that are hallmarks of the disease." (PMID 33557244, 2021). "In fact, the mouse with the retrotransposon insertion into the Sil1 gene was referred to as the “woozy” mouse (Sil1wz) due to the early onset of ataxia." (PMID 33557244, 2021). "SIL1 mutations are identified in about 50–60% of patients with the characteristic MSS triad (myopathy, early-onset cataracts, and cerebellar ataxia)." (PMID 28052128, 2017). "All eight patients analyzed for SIL1 mutations presented key clinical features of MSS, including MR, cerebellar ataxia with cerebellar atrophy, bilateral cataracts and myopathy." (PMID 24473200, 2014). "While most SIL1 pathogenic variant-positive MSS patients exhibit hallmark clinical features such as intellectual disability (ID), myopathy, cerebellar atrophy, ataxia, and cataracts, the additional features and their severity can vary between patients, seemingly depending on the type of variant." (PMID 41465794, 2025). "While most SIL1 mutation-positive MSS patients show the hallmark clinical features such as MR, myopathy, cerebellar atrophy and ataxia, and cataracts, additional features and their severity vary from patient to patient, seemingly depending on the mutation type at least to some extent." (PMID 24473200, 2014). "Three of the 27 patients (11.1%) had no SIL1 mutation, but demonstrated the cardinal features of MSS, including congenital cataracts, ataxia, intellectual disability, and myopathy." (PMID 24755310, 2014).
cataract (8 papers, 2010 to 2024). Partial or complete opacity of the crystalline lens of one or both eyes that decreases visual acuity and eventually results in blindness. "Almost all the MSS patients with SIL1 mutations in this series had muscle weakness initially noticed as a delayed motor milestone, which was detected at an earlier age than cataracts." (PMID 24755310, 2014). "Interestingly, sil1 morphants showed smaller-sized eyes instead of cataracts, which suggests that sil1 may have important roles in development of eyes in zebrafish." (PMID 27792754, 2016).
Cerebellar atrophy (5 papers, 2006 to 2024). Cerebellar atrophy is defined as a cerebellum with initially normal structures, in a posterior fossa with normal size, which displays enlarged fissures (interfolial spaces) in comparison to the foliae secondary to loss of tissue. "The SIL1-disrupted animal model, woozy mice, show characteristic cerebellar atrophy, which is a major symptom of MSS patients, and abnormal protein accumulation and neurodegeneration in cerebellar Purkinje cells." (PMID 24473200, 2014).
amyotrophic lateral sclerosis (4 papers, 2016 to 2021). Amyotrophic lateral sclerosis (ALS) is a neurodegenerative disease characterized by progressive muscular paralysis reflecting degeneration of motor neurons in the primary motor cortex, corticospinal tracts, brainstem and spinal cord. "Since SIL1 plays a crucial role in maintaining ER homeostasis in neurons, it did not come as a complete surprise when SIL1 was implicated as a modifier in amyotrophic lateral sclerosis (ALS)." (PMID 33557244, 2021). "The Amyotrophic lateral sclerosis (ALS)-vulnerable FF motor neurons have much less SIL1 compared to the disease-resistant S motor neurons, and this difference is the main reason for the different resistance of the two types of neurons against ALS." (PMID 31531014, 2019). "Recently SIL1 was reported to play a role in regulation of motor neuron subtype-selective ER stress in amyotrophic lateral sclerosis (ALS)." (PMID 27792754, 2016). "Moreover, a particular function of Sil1 for etiopathology of two neurodegenerative disorders, amyotrophic lateral sclerosis (ALS) and Alzheimer disease was highlighted, thus declaring the functional Sil1-BiP complex as a modifier for neurodegenerative disorders." (PMID 33925740, 2021).
Intellectual disability (4 papers, 2014 to 2024). "Sil1 is the only gene found to be responsible for the MSS which has a major symptom of mental retardation." (PMID 31531014, 2019). "Mental retardation is one of the major symptoms of MSS which indicated that SIL1 might play important roles in neurons." (PMID 31531014, 2019). "Mental retardation is a major symptom of MSS which suggests a role of SIL1 in the development of the central nervous system, but how SIL1 functions remains unclear." (PMID 31531014, 2019).
Alzheimer disease (3 papers, 2021). A progressive, neurodegenerative disease characterized by loss of function and death of nerve cells in several areas of the brain leading to loss of cognitive function such as memory and language. "In fact, total SIL1 levels were also found to be decreased in the cortex and hippocampus of a murine model of Alzheimer’s disease (Tg2576), whereas the surviving hippocampal neuronal population in Alzheimer’s disease autopsies displayed higher SIL1 levels." (PMID 33557244, 2021).
autosomal recessive cerebellar ataxia (1 paper, 2023). "The known FEM1C substrates include SIL1, a nucleotide exchange factor for the BiP endoplasmic reticulum chaperone associated with Marinesco-Sjögren syndrome—an autosomal recessive cerebellar ataxia." (PMID 36336956, 2023). "A misregulation of SIL1, which is linked to an autosomal recessive cerebellar ataxia and DD, might be a possible cause of the diseases associated with FEM1CAsp126His or FEM1CAsp126Val mutations." (PMID 36336956, 2023).
bipolar disorder (1 paper, 2025). A disorder of the brain that causes unusual shifts in mood, energy, activity levels and the ability to carry out day-to-day tasks. "In bipolar disorder, we identified common oligodendrocyte-specific differentially acetylated peaks in the vicinity of AP1S2, SIL1, and EDAR, while controlling for CHAS scores and MF proportions, respectively." (PMID 40300607, 2025).
endometriosis (1 paper, 2010). The growth of functional endometrial tissue in anatomic sites outside the uterine body. "Our results suggest that sIL-1 RII treatment throughout the development of endometriosis decreases the expression of VEGF protein, which then affects the angiogenesis of the lesions." (PMID 23554610, 2010). "The purpose of this study was to evaluate the therapeutic potential of sIL-1 RII in counteracting the effect of IL-1 using an in vivo nude mouse model of experimentally-induced endometriosis." (PMID 23554610, 2010). "Although the cytokine network in the endometrium is complex, our results provide further insights into the mechanism of immunologic modulation of sIL-1 RII during the process of endometriosis." (PMID 23554610, 2010). "Now, we have found that in an endometriosis nude mice model, the IL-8 concentration in the peritoneal fluid and serum of the sIL-1 RII treated group is significantly lower than the other two groups, and is in fact increased in the IL-1 treated group." (PMID 23554610, 2010). "Our results suggest that sIL-1 RII may provide a new clinical strategy for the treatment of endometriosis." (PMID 23554610, 2010). "Recent studies have shown that the local expression of soluble interleukin (IL) -1 receptor type II (sIL-1 RII) in endometrial tissue of women with endometriosis is decreased, and the depression of IL-1 RII was more significant in infertile women than that in fertile women with endometriosis." (PMID 23554610, 2010). "sIL-1 RII may suppresse hyperplasia of ectopic endometriosis, perhaps by reducing the expression of certain cytokines, such as VEGF, IL-8, and Bcl-2, which could provide a new clinical strategy for the treatment of endometriosis." (PMID 23554610, 2010). "Our results demonstrate that in the formed lesions, sIL-1 RII decreased the expression of Bcl-2 and VEGF compared with both control and IL-1 groups, and may contribute to decreasing the size of already formed lesions in the endometriosis nude mouse model." (PMID 23554610, 2010).
glioblastoma (1 paper, 2021). The most malignant astrocytic tumor (WHO grade IV). "While the expression of SIL1 demonstrates low cancer specificity, a recent study found that SIL1 was expressed at higher levels in ~66% of glioblastoma multiforme and lower-grade gliomas compared to normal tissue, and it was particularly high in grade IV gliomas compared to grades I-III." (PMID 33557244, 2021).
mastitis (1 paper, 2020). Inflammation of breast tissue during lactation or postpartum due to an obstructed duct or infection. "Among the highly connected genes in the magenta module, GCLM, PARK7, SIL1, PHB, and CD68 were potentially associated with mastitis or similar biological processes, based on the previous studies." (PMID 32754201, 2020).
mental disorder (1 paper, 2016). A disease that has its basis in the disruption of mental process.
microcephaly (1 paper, 2014). A congenital or acquired developmental disorder in which the circumference of the head is smaller than normal for the person's age and sex. "Morphological analyses of the microcephaly by autopsy are essential for the elucidation of pathophysiological roles of SIL1 mutations in neurodegeneration of MSS." (PMID 24473200, 2014).
mtDNA depletion syndrome (1 paper, 2019). "Notably, in the study of SIL1 negative, atypical MSS patients, one patient was ultimately diagnosed with an AGK-related mtDNA depletion syndrome." (PMID 31463572, 2019).
Saul-Wilson syndrome (1 paper, 2021). "Interestingly, the Saul-Wilson syndrome presents skeletal and ocular defects similar to SIL1 mutation (loss of function) phenotypes." (PMID 34603392, 2021). "Therefore, SIL1 mutation could be the major contributing factor to Saul-Wilson syndrome." (PMID 34603392, 2021).
tuberculosis (1 paper, 2024). A chronic, recurrent infection caused by the bacterium Mycobacterium tuberculosis. "The results of ROC showed that TYMP (AUC = 0.964), LAP3 (AUC = 0.914), ADGRL2 (AUC = 0.98), SIL1 (AUC = 0.936), LMO7 (AUC = 0.856), SULF1 (AUC = 0.96), ANXA3 (AUC = 0.798), and PACSIN3 (AUC = 0.747) had high accuracy in predicting tuberculosis." (PMID 39023413, 2024).
myopathy (10 papers, 2010 to 2022). A disease of the muscle in which the muscle fibers do not function properly. "Proteomic profiling of quadriceps at the onset of myopathy revealed that SIL1 deficiency affected multiple pathways critical to muscle physiology." (PMID 29666155, 2018). "Editor's choice: This study provides molecular insights into the progressive myopathy and cellular compensatory responses attempted upon loss of SIL1, a component of the endoplasmic-reticulum-resident Hsp70 protein-folding machinery." (PMID 29666155, 2018). "Together, these data reveal a disruption in ER homeostasis upon SIL1 loss, which is countered by multiple compensatory responses that are ultimately unsuccessful, leading to trans-organellar proteostasis collapse and myopathy." (PMID 29666155, 2018). "Two studies using different mouse models demonstrated that Sil1 disruption in mice phenocopies the ultrastructural features of the progressive myopathy observed in MSS patients and have proved useful for molecular and longitudinal studies of the myopathy." (PMID 33557244, 2021). "Forty-six candidate genes are prioritized by multiple approaches (42 for LST and 6 for MVPA; 2 overlap) and point to endocytosis (CNIH2, RAB1B, KLC2, PACS1, REPS1, DNM3, EXOC4), locomotion (CADM2, KLC2) and myopathy (MLF2, HERC1, KLC2, SIL1) as relevant pathways." (PMID 36071172, 2022).
neurodegenerative disease (3 papers, 2014 to 2021). A disorder of the central nervous system characterized by gradual and progressive loss of neural tissue and neurologic function. "The involvement of impaired BiP function in neurodegenerative diseases has been reported in a mouse model where the disruption of SIL1, a co-chaperone of BiP, causes protein accumulation and neurodegeneration." (PMID 25405877, 2014). "Next, since the SIL1-HSPA5 chaperone system is involved in cell stress and MSS is thought to be a neurodegenerative disease, we evaluated whether apoptosis takes place in SIL1-deficient neurons." (PMID 24473200, 2014). "There is another functional homolog to bacterial GrpE in the ER lumen (termed Sil1 or BAP), i.e., there is redundancy also at the level of the NEFs, which may explain the non-lethal phenotype of loss of Sil1 function that is associated with the neurodegenerative disease, Marinesco–Sjögren syndrome." (PMID 33925740, 2021).
cancer (2 papers, 2021 to 2025). A tumor composed of atypical neoplastic, often pleomorphic cells that invade other tissues. "Future research should focus on functional characterization of VUS in genes like SIL1, SNX14, and ALOX12B to elucidate their potential role in cancer pathways." (PMID 41229501, 2025).
genetic disorder (2 papers, 2022 to 2025). "This rare genetic disorder is caused by mutations in the SIL1 gene in about 60% of cases, which encodes the nucleotide exchange factor SIL1, an essential component of the endoplasmic reticulum protein quality control machinery." (PMID 41350949, 2025).
neuromuscular disease (2 papers, 2025). "MSS is an early-onset neuromuscular disease caused by variants of the SIL1 gene in about half of the cases, while the gene(s) responsible for the other cases is (are) still unknown." (PMID 41373471, 2025). "MSS is a neuromuscular disease triggered by the loss of the ER co-chaperone Sil1." (PMID 40216824, 2025).
SIL1 also shares sentences with these, for which no sentence is quoted: cerebellar ataxia (7 papers); congenital cataracts (4); Aortic root aneurysm (1); coronary artery atherosclerosis (1); developmental delay (1); diabetes mellitus (1); dissection (1); glioma (1); hypogonadism (1); hypotrichosis (1); infection (1); infertile (1); liposarcoma (1); mesothelioma (1); neutropenia (1); Onset (1); onychodysplasia (1); Paroxysmal atrial fibrillation (1); Peripheral arterial stenosis (1); Sjogren syndrome (1); SOFT syndrome (1).